EGFR (epidermal growth factor receptor)
Diseases named in the same sentence as EGFR in open-access papers (continued):
Sharing a sentence is not in itself a finding about the gene and the disease.
thymoma (25 papers, 2014 to 2025). A neoplasm arising from the epithelial cells of the thymus. "The growth and metastasis of thymoma cells is associated with the activation of the EGFR signaling pathway." (PMID 41472727, 2025). "Our research screened out the core target genes AKT1, MMP9, STAT3, SRC, and EGFR of thymoma-associated M, and carried out molecular docking verification." (PMID 37498332, 2024). "EGFR expression is lower in thymic carcinomas compared to thymomas, and somatic mutations in EGFR are infrequent, which explains the limited efficacy of EGFR inhibitors in thymic epithelial tumors." (PMID 38201593, 2023). "Recent studies have reported that EGFR can be expressed in thymoma, which is an important cause of myasthenia gravis, and that EGFR overactivates the downstream PI3K/Akt/mTOR signalling pathway, inhibits apoptosis, and stimulates tumor growth." (PMID 36818231, 2023). "EGFR is highly expressed in some thymoma and TC samples, but only a few mutations have been identified within EGFR in thymoma samples." (PMID 34568003, 2021). "Although EGFR mutations are rare in TETs, the receptor has been shown frequently overexpressed in thymomas and thymic carcinomas." (PMID 28486946, 2017). "Several studies have reported that EGFR is overexpressed in thymomas and TCs, with higher EGFR staining significantly associated with stage III-IV cases." (PMID 27387303, 2016). "Notably, EGFR mutations are exceedingly rare occurrences, and although EGFR amplification has been observed in B3-type thymomas, its association with EGFR expression remains elusive." (PMID 37849766, 2023). "Membrane associated EGFR expression has been seen in thymomas as well as in thymic carcinomas." (PMID 24934485, 2014). "Although EGFR-targeted drugs, such as erlotinib, can be effective against thymoma cells, their scope is limited due to the complex molecular and biological characteristics of thymomas." (PMID 41472727, 2025). "EGFR-targeted drugs and PD-1 inhibitors can not only reduce the proliferation of thymoma cells by inhibiting the EGFR signaling pathway but also relieve the immunosuppressive microenvironment and improve anti-tumor immune responses." (PMID 41472727, 2025). "Numerous studies reported the overexpression of EGFR in thymomas via immunohistochemistry (IHC) analysis resulting in the clinical trial exploration of EGFR targeting agents." (PMID 38254905, 2024). "Case reports noted the potential use of cetuximab, which is an EGFR-targeting monoclonal antibody, in EGFR-expressing thymomas." (PMID 38254905, 2024). "Immunohistochemical analysis has revealed EGFR overexpression in 70% of thymomas and 53% of thymic carcinomas, with higher EGFR staining levels demonstrating a notable correlation with advanced stage III to IV tumors." (PMID 37849766, 2023). "Currently, some genetic and epigenetic alternations such as epidermal growth factor receptor amplification, HER2/neu over expression, and c-Kit (CD 117) activating mutation has been considered in thymoma pathogenesis." (PMID 32607118, 2019). "At present, another phase II study is evaluating bevacizumab in combination with anti-EGFR TKI erlotinib in patients with advanced thymoma and TC (NCT00369889)." (PMID 26254278, 2015). "Only a small proportion of thymoma patients with high EGFR expression may benefit from EGFR-targeted therapy." (PMID 41472727, 2025). "Notably, cetuximab demonstrated partial response in recurrent thymomas after extensive pretreatment, all of which expressed robust EGFR." (PMID 38338833, 2024).
thymoma (continued). "By the ssGSEA method, we proved that CTNNB1, EGFR, SOX2, and ERBB2 expressions showed significant correlation with Th17 T cell in thymoma, and KEGG analysis suggested that differential genes were highly enriched in the IL-17 pathway." (PMID 39192657, 2025). "EGFR, a member of the ErbB family (HER1), is overexpressed in 33–100% of thymomas and 33–83% of thymic carcinomas." (PMID 41300989, 2025). "About 20% of thymic malignancies exhibit EGFR gene amplification by fluorescence in situ hybridization (FISH), most frequently in type B3 thymoma and TC, related to more advanced stage and capsule invasion." (PMID 37893096, 2023). "We next evaluated the effect of combined therapy of VPA plus Erlotinib, an EGFR tyrosine kinase inhibitor, being Erlotinib under investigation as potential therapeutic agent in TET, especially in patients with heavily pretreated thymoma." (PMID 28486946, 2017). "CTNNB1, EGFR, SOX2, and ERBB2 expressions revealed a significant correlation with NK cells in thymoma, and these four genes may play a role in regulating NK cells in TAMG." (PMID 39192657, 2025). "EGFR protein overexpression is present in approximately 70% of thymomas and 50% of TC without any relationship with the histologic subtype." (PMID 37893096, 2023). "Also targeted therapy has recently emerged in TET management and the use of EGFR-tyrosine kinase inhibitors (TKI) (Erlotinib or Gefitinib) or anti-EGFR mAb (Cetuximab) are currently under investigation as potential therapeutic agents in TET, especially in patients with heavily pretreated thymoma." (PMID 28486946, 2017).
basal cell carcinoma (24 papers, 2013 to 2026). A carcinoma involving the basal cells. "Additional markers used mainly for basal cell carcinoma stratification include Ki-67, EGFR (epidermal growth factor receptor) and basal cytokeratins (CK5/6, CK14, C19)." (PMID 36358862, 2022).
neutropenia (24 papers, 2013 to 2025). A decrease in the number of neutrophils found in the blood. "We conducted a retrospective observational study of hypomagnesemia caused by anti-EGFR antibodies, and neutropenia caused by Trifluridine-tipiracil (TAS-102) in relation to treatment response." (PMID 39696667, 2024). "Incidence of hypomagnesemia in patients receiving anti-EGFR antibodies and neutropenia in patients receiving TAS-102 was significantly associated with the therapeutic effect of cancer chemotherapy." (PMID 39696667, 2024). "TKI turned out to be the most effective drug reducing the incidence of fatigue and diarrhoea, while EGFR was associated with less neutropenia events and thrombocytopenia compared with other treatments." (PMID 28477027, 2017). "M-TOR invited more thrombocytopenia events than EGFR (OR = 5.37, 95% CrI = 1.11–37.71) and was associated with higher risk of neutropenia compared to placebo and EGFR (OR = 12.81, 95% CrI = 1.23–432.68; OR = 13.46, 95% CrI = 1.13–487.85, respectively)." (PMID 28477027, 2017). "In the real-world setting, a previous study reported neutropenia (13.2%) and gastrointestinal upset (10.5%) as the most common treatment toxicities when combining EGFR TKI with crizotinib." (PMID 40470164, 2025). "Two studies reported the grades 3 and 4 diarrhea and neutropenia between FOLFOXIRI + anti-EGFR antibody arm and FOLFOXIRI arm." (PMID 37978547, 2023). "These anti-EGFR TKIs have demonstrated a favorable hematologic toxicity profile (e.g. less grade 3–4 neutropenia and thrombocytopenia) compared to the chemotherapeutic alternatives and can provide a treatment alternative in patients in whom a break from chemotherapy is preferred." (PMID 30973926, 2019). "Interestingly, however, the addition of an anti-EGFR agent significantly reduced the rate of grade 3/4 neutropenia (RR = 0.68 [95% CI, 0.52–0.89], P = 0.004)." (PMID 29228748, 2017). "With regard to neutropenia, pooled occurrence rates for VEGF and EGFR inhibitors were 34% (95% CI: 9%, 60%) and 47% (95% CI: 24%, 71%)." (PMID 37324019, 2023). "Triplet-drug chemotherapy combined with anti-EGFR antibody scheme seems not to increase toxicity (diarrhea or neutropenia) significantly than triplet-drug chemotherapy." (PMID 37978547, 2023). "In general, the non-maintenance cohort had higher incidence rates of any grade non-hematological and hematological AEs, diarrhea, and neutropenia compared to those of the 5FU/LV+anti-EGFR and anti-EGFR cohorts." (PMID 34778029, 2021). "Regarding the concern of neutropenia, an increased incidence of bevacizumab-related neutropenia mainly occurred with the combination with cytotoxic chemotherapy, but not with EGFR-TKIs." (PMID 33113888, 2020). "Compared with DPF, the NPF regimen effectively alleviated neutropenia (P = 0.018) and gastrointestinal reactions (P = 0.032) in the induction phase, while use of EGFR monoclonal antibody in human chemotherapy did not increase mucosal-related toxicity." (PMID 31888551, 2019). "However, while the successful rate of combination Gem plus erlotinib is strictly dependent on the EGFR status and other potential signatures, serious side effects have been reported in PDAC patients treated with Gem plus nab-paclitaxel, including neutropenia, peripheral neuropathy, and fatigue." (PMID 35273510, 2022).
stomatitis (24 papers, 2014 to 2026). Inflammation of the oral mucosa due to local or systemic factors. "As with other EGFR-TKI-associated AEs, it is suggested that treatment with the EGFR TKI be paused until severe cases of stomatitis/mucositis are resolved or improved." (PMID 30588353, 2018). "We further analyzed six commonly reported TRAEs for EGFR TKIs, including rash, diarrhea, stomatitis, elevated creatine phosphokinase (CPK), elevated alanine aminotransferase (ALT), and thrombocytopenia." (PMID 41211184, 2025). "As expected, a higher incidence of AEs, particularly diarrhea and stomatitis (42% vs. 20%), as well as of anti-EGFR-related AEs (76% vs. 42%), was found with 5FU/LV+panitumumab compared to that with panitumumab alone." (PMID 34778029, 2021). "Gastrointestinal events are frequent during EGFR-TKIs treatment, including stomatitis, nausea, and diarrhea, vomiting, and decreased appetite, of which diarrhea is the most common event." (PMID 32179761, 2020). "Stomatitis (inflammation of the mouth) and mucositis (inflammation of the gastrointestinal tract) have been observed with EGFR-TKIs." (PMID 30588353, 2018). "There have not been any randomized control trials to determine the best ways to manage EGFR–TKI induced mucositis/stomatitis." (PMID 25279350, 2014). "As an EGFR- and MET-targeting therapy, amivantamab is associated with various AEs, including skin reactions, peripheral edema, hypoalbuminemia, IRRs, gastrointestinal AEs, and stomatitis." (PMID 40592737, 2025). "Mucositis and stomatitis can be troublesome for patients receiving EGFR TKI therapy." (PMID 29670808, 2016). "EGFR–TKI is maintained for grades 1 and 2, and temporarily discontinued for grade 3, until the stomatitis/mucositis improves to grade 2, at which point it is resumed at 50% of the original dose and then increased if symptoms do not get worse." (PMID 25279350, 2014).
breast adenocarcinoma (23 papers, 2009 to 2026). "In previous studies, we found that the binding of natural compounds to EGFR, causing a decrease in EGFR phosphorylation, inhibited the proliferation, migration, invasion, and angiogenesis of human breast adenocarcinoma cells." (PMID 32204508, 2020). "Previously, using HER2+ breast adenocarcinoma cell line SK-BR-3, we observed a noteworthy reduction in the inhibitory effects of the EGFR/HER2-targeting drug lapatinib on cell growth when human blood serum was present in the growth media." (PMID 39403185, 2024). "Total bound immunoglobulin in the form of gemcitabine-(C4-amide)-[anti-HER2/neu] or gemcitabine-(C4-amide)-[anti-EGFR] on the external surface membrane of adherent mammary adenocarcinoma (SKBr-3) populations was measured by cell-ELISA." (PMID 25821636, 2015). "Anti-neoplastic cytotoxicity of gemcitabine-(C4-amide)-[anti-EGFR] against chemotherapeutic-resistant mammary adenocarcinoma (SKBr-3) was consistently greater with incubation periods of 182-hours compared to 96-hours." (PMID 25821636, 2015). "Anti-neoplastic cytotoxic potency was determined by vitality stain analysis of chemotherapeutic-resistant mammary adenocarcinoma (SKBr-3) monolayers known to uniquely over-express EGFR (2 × 105/cell) and HER2/neu (1 × 106/cell) receptor complexes." (PMID 25844392, 2014). "In mammary adenocarcinoma (SKBr-3) EGFR (2.2 × 105/cell) is over-expressed and HER2/neu (1 × 106/cell) is highly over-expressed compared to normal/healthy tissues and organ systems." (PMID 25844392, 2014). "Although specific data for HER2/neu and EGFR expression by mammary adenocarcinoma (SKBr-3) is limited, other neoplastic cell types like metastatic multiple myeloma are known to internalize approximately 8×106 molecules of anti-CD74 monoclonal antibody per day." (PMID 26225219, 2013). "Similarly, gemcitabine-(C4-amide)-[anti-EGFR] produced measurably higher levels of canti-neoplastic cytotoxicity when incubated with chemotherapeutic-resistant mammary adenocarcinoma (SKBr-3) for direct contact periods of 182-hours compared to 96-hours." (PMID 25821636, 2015). "Gemcitabine-(C4-amide)-[anti-EGFR] produced greater anti-neoplastic cytotoxicity than either gemcitabine (C5-methylcarbamate)-[anti-HER2/neu] or gemcitabine-(C4-amide)-[anti-HER2/neu] against chemotherapeutic-resistant mammary adenocarcinoma (SKBr-3) during an 182-hour incubation period." (PMID 25821636, 2015). "A human neoplastic cell type other than chemotherapeutic-resistant mammary adenocarcinoma (SKBr-3) could have been applied to access anti-neoplastic cytotoxicity of gemcitabine-(C4-amide)-[anti-EGFR] in dual simultaneous combination with gemcitabine-(C4-amide)-[anti-HER2/neu]." (PMID 25821636, 2015). "The dual-combination of gemcitabine-(C4-amide)-[anti-EGFR] with epirubicin-(C3-amide)-[anti-HER2/neu] produced higher levels of selectively “targeted” anti-neoplastic cytotoxicity against chemotherapeutic-resistant mammary adenocarcinoma (SKBr-3) than either covalent immunochemotherapeutic alone." (PMID 25844392, 2014). "It is known that breast adenocarcinoma MCF7 cells can spontaneously form 3D spheroids and such spheroids are characterized by high expression of EGFR/HER2, while the natural phenotype of MCF7 cells is EGFRlow/HER2low." (PMID 34884742, 2021). "Total bound immunoglobulin in the form of gemcitabine-(C4-amide)-[anti-EGFR] and epirubicin-(C3-amide)-[anti-HER2/neu] on the external surface membrane of adherent mammary adenocarcinoma (SKBr-3) populations was measured by cell-ELISA (Figure." (PMID 25844392, 2014). "The human mammary adenocarcinoma cell line MDA-MB-468 was selected as suitable model for method evaluation, since it harbors an EGFR amplification and shows strong EGFR overexpression as well as displays a stemness/committed progenitor cell phenotype." (PMID 22140428, 2011).
breast adenocarcinoma (continued). "We find that, similar to its regulation in osteoblasts, RUNX2 expression in MDA-MB-231 breast adenocarcinoma cells is enhanced upon growth factor deprivation, as well as upon deactivation of the mitogen-dependent MEK-Erk pathway or EGFR signaling." (PMID 21029421, 2010). "The covalent immunochemotherapeutics, gemcitabine-(C4-amide)-[anti-EGFR] and gemcitabine-(C4-amide)-[anti-HER2/neu] each have potent selective “targeted” anti-neoplastic cytotoxic properties against chemotherapeutic-resistant mammary adenocarcinoma (SKBr-3)." (PMID 25821636, 2015). "Total anti-neoplastic cytotoxicity of the dual simultaneous combination of gemcitabine-(C4-amide)-[anti-EGFR] and gemcitabine-(C4-amide)-[anti-HER2/neu] against chemotherapeutic-resistant mammary adenocarcinoma (SKBr-3) was substantially higher when formulated with [Se]-methylsele-nocysteine." (PMID 25821636, 2015). "The covalent immunochemotherapeutics, gemcitabine-(C4-amide)-[anti-EGFR] and epirubicin-(C3-amide)-[anti-HER2/neu] both exerted selectively “targeted” anti-neoplastic cytotoxicity against chemotherapeutic-resistant mammary adenocarcinoma (SKBr-3) populations (Figures." (PMID 25844392, 2014). "Cytotoxic anti-neoplastic potency of gemcitabine-(C4-amide)-[anti-EGFR] and gemcitabine-(C4-amide)-[anti-HER2/neu] between gemcitabine-equivalent concentrations of 10−12 M and 10−6 M was determined utilizing chemotherapeutic-resistant mammary adenocarcinoma (SKRr-3)." (PMID 25821636, 2015).